PINK1 (PTEN induced kinase 1)
Diseases named in the same sentence as PINK1 in open-access papers (continued):
Sharing a sentence is not in itself a finding about the gene and the disease.
Parkinson disease (continued). "Wider genetic analyses of EOPD in North Africa would be useful to estimate the prevalence of Parkinsonism caused by PINK1 p.A217D." (PMID 28789629, 2017). "The PINK1/Parkin-mediated pathway is closely associated with Parkinson's disease and is a topic of current research." (PMID 29391926, 2017). "Mutations in genes encoding the parkin and PINK1 proteins were first identified in the pathogenesis of Parkinson's diseases and determined to be involved in the underlying mechanisms of several other major neurodegenerative diseases." (PMID 29201272, 2017). "Despite the epidemiological association between Parkinson's diseases and heart failure, the indispensable roles of parkin and PINK1 for normal heart function have come under intense attack in the past decade." (PMID 29201272, 2017). "Mutations of PTEN-induced kinase 1(PINK1) gene, which encodes a mitochondrial Ser/Thr protein kinase, cause the autosomal recessive familial type 6 of Parkinson’s disease (PARK6)." (PMID 29108286, 2017). "Mutations in PTEN‐induced putative kinase 1 (PINK1) are a cause of early onset Parkinson's disease (PD)." (PMID 27859782, 2017). "Some cases of parkinsonism are caused by autosomal recessive mutations in mitophagy related proteins, such as PINK1 and Parkin." (PMID 28933354, 2016). "Loss-of-function mutations in either PINK1 or Parkin are the cause of familial cases of Parkinson's Disease (OMIM 608309 and 602544) implicating defects in this pathway, in the pathogenesis of this form of neurodegeneration." (PMID 27242399, 2016). "PINK1 is the second most common pathogenic gene associated with autosomal recessive, early onset Parkinson’s disease." (PMID 28536620, 2016). "The clinical presentation in our patient with this novel homozygous p.L539F mutation was typical with the classical clinical triad of Parkinson's disease but was slightly different from that due to the already reported PINK1 mutations." (PMID 27413743, 2016). "Mutations affecting PINK1–Parkin genes cause Parkinson’s disease (PD; a neurodegenerative illness characterized by accumulation of dysfunctional mitochondria)." (PMID 27199746, 2016). "One of the most described pathways of mitophagy is the PINK1/Parkin-mediated autophagy; notably, mutations in the Parkin and PINK1 genes are the most common causes of recessive forms of Parkinson's Disease characterized by early onset." (PMID 26977249, 2016). "Mutations in the PINK1 and Parkin genes are well known causes of autosomal recessive forms of Parkinson’s disease, and numerous studies link this to the role of these proteins in mitochondrial quality control." (PMID 28933354, 2016). "PINK1 is genetically associated with Parkinson’s disease (PD) and plays critical roles in maintaining mitochondrial homeostasis." (PMID 27456084, 2016). "In human, the mutations of phosphatase and tensin homolog (PTEN)-induced putative kinase 1 (PINK1) and Parkin are linked to autosomal recessive forms of Parkinson's disease." (PMID 27463011, 2016). "The PINK1/Parkin pathway involves the interplay of two recessive Parkinson’s-linked genes [PTEN-induced kinase 1 (PINK1) and Parkin (an E3 ubiquitin ligase)], which maintain mitochondrial homeostasis and clear dysfunctional mitochondria via mitophagy." (PMID 27199746, 2016). "It is suggested that disrupted mitophagy induction results in blunted mitochondrial turn-over and subsequently leads to the aggregation of defected mitochondria in Parkinson’s disease (PD) patients with mutations in Parkin and/or PINK1." (PMID 26942905, 2016). "Previous work by our lab has categorized the mitochondrial disorder associated with Parkinson׳s disease in a PINK1 knockout rat model." (PMID 26866053, 2016). "Interruption of PINK1/Parkin-mediated mitophagy, as by loss-of-function Parkinson's disease mutations, suppresses a major mechanism for maintaining the overall quality of mitochondrial health: selective elimination of dysfunctional mitochondria." (PMID 25861797, 2015).
Parkinson disease (continued). "Mutations in PINK1 and Parkin are associated with mitochondrial dysfunction and neurodegenerative diseases such as Parkinson’s disease." (PMID 26161534, 2015). "Increased levels of ROS, the principle known inducer of uncoupling protein 2 (UCP2), which typically mediates inducible proton leak, have been measured in pink-1 deficient cell lines and in mitochondria isolated from Parkinson’s disease patients." (PMID 26106885, 2015). "This phenotype is reminiscent of the effects of loss-of-function mutants for the two Parkinson’s disease susceptibility genes, Pink1 and Parkin, which also have selective effects on mitochondria in IFMs and a flightless phenotype." (PMID 26599788, 2015). "Mutations of the PTEN-induced putative kinase 1 (PINK1) gene are a cause of autosomal recessive forms of Parkinson’s disease." (PMID 26555609, 2015). "Because patients with familial parkinsonism present symptoms similar to sporadic Parkinson's disease, functional analysis of familial Parkinson's disease-related proteins such as PINK1 provides insights into the pathogenic mechanism of the disease." (PMID 25609704, 2015). "Recessively inherited forms of Parkinson's disease are associated with loss-of-function mutations of the PTEN-induced kinase 1 (PINK1) and the E3 ubiquitin ligase Parkin." (PMID 26793123, 2015). "Post‐mortem analysis of brains from a family with Parkinsonism harbouring PINK1 mutations has confirmed the presence of Lewy bodies in the substantia nigra." (PMID 26471730, 2015). "Mitophagy is regulated by the kinase PINK1 and the ubiquitin ligase Parkin, proteins encoded by genes that when mutated lead to early onset Parkinsonism." (PMID 25857750, 2015). "Epidemiologically, mutations of the Parkin gene are the major cause of early-onset hereditary Parkinson's disease; PINK1 gene mutations are a less common cause." (PMID 25861797, 2015). "Mutations in genes encoding the protein kinase PTEN-induced kinase 1 (PINK1) and the ubiquitin E3 ligase, Parkin, are causal for early-onset Parkinson's disease (PD)." (PMID 26116755, 2015). "The PARK2 (Parkin) and PARK6 (PINK1) gene products were originally identified as mutated in human Parkinson’s disease (PD) and subsequently shown to function in concert to promote mitophagy, thus implicating dysfunctional mitochondria in the etiology of PD." (PMID 25810907, 2015). "PINK1 and Park's molecular mechanisms are particularly relevant to Parkinson's disease, given that inherited mutations in PARK2 and PINK1 can cause early-onset Parkinsonism." (PMID 26035866, 2015). "Several other proteins were implicated in oxidative stress—induced Parkinson’s disease, including pink-1 and LRK-1." (PMID 26114733, 2015). "Loss-of-function mutations in PINK1 or Parkin cause mitochondrial dysfunction, and are directly linked to Parkinson’s disease." (PMID 26161534, 2015). "We further show that glycolic acid and D-lactic acid can elevate lowered mitochondrial membrane potential caused by silencing PINK-1, another Parkinson's related gene, as well as by paraquat, an environmental toxin known to be linked with Parkinson's disease." (PMID 25063200, 2014). "PD caused by mutations in PARK2 has been suggested to have much in common with other early onset autosomal recessive forms of parkinsonism caused by mutations in PINK1/PARK6 or DJ-1/PARK7." (PMID 24115276, 2014). "The PINK1−/− mice is a model of the autosomal recessive PARK6-linked Parkinsonism, an early-onset variant of familial PD caused by loss-of-function mutations in the mitochondrial protein PINK1." (PMID 24904316, 2014). "Two genes linked to early onset Parkinson's disease, PINK1 and Parkin, encode a protein kinase and a ubiquitin-ligase, respectively." (PMID 24901221, 2014). "Loss-of-function mutations in PINK1, which encodes a mitochondrially targeted serine/threonine kinase, result in an early-onset heritable form of Parkinson's disease." (PMID 24874806, 2014).
Parkinson disease (continued). "PINK1 driven phosphorylation of ubiquitin has important implications in understanding the underlying pathophysiological mechanisms of parkinsonism and to develop new treatment strategies for an incurable movement disorder." (PMID 25505445, 2014). "Two major mitophagy-related proteins, Parkin and PTEN-induced putative kinase protein 1 (PINK1), have been linked to the pathogenesis of Parkinson’s disease." (PMID 25414669, 2014). "Since we found the PINK1 gene, which is associated with Parkinson's disease, present in our analyses, we wanted to identify the diseases, if any, that were associated with the low TO genes." (PMID 25147748, 2014). "Mutations in phosphatase and tensin homologue-induced kinase 1 (PINK1) cause recessively inherited Parkinson's disease, a neurodegenerative disorder linked to mitochondrial dysfunction." (PMID 23533695, 2013). "Mutations in the PINK1 gene are responsible for the autosomal recessive PARK6 inherited form of early onset Parkinson disease, a neurodegenerative disorder characterized by the loss of dopaminergic neurons in the substantia nigra." (PMID 23638067, 2013). "Mitophagy defects are seen in Parkinson's disease model where there are mutations in PINK1 and Parkin." (PMID 24288463, 2013). "Impairment of this process by mutations in mitophagy-mediating genes such PINK1 or Parkin is linked to hereditary forms of Parkinson's disease, a neurodegenerative disorder, emphasizing the vital role of mitochondrial homeostasis in cell survival." (PMID 24339771, 2013). "For example, the dopaminergic neurons differentiated from hiPSCs carrying a mutation in the PINK1 gene (causes Parkinson's disease) only showed altered patterns of survival when additionally treated with a mitochondrial stressor." (PMID 22886688, 2013). "For Parkinson's disease mutations in PINK1 and parkin have implicated the degradation of damaged mitochondria through autophagy as part of the pathogenesis." (PMID 23524341, 2013). "As neurons are destined to degenerate in PINK1/Parkin-associated Parkinsonism, it is imperative to investigate the function of PINK1 and Parkin in neurons." (PMID 23751051, 2013). "When mitochondrial import is compromised by depolarization, PINK1 accumulates on the mitochondrial surface, where it recruits the Parkinson's disease-linked Parkin from the cytosol, which in turn mediates the mitophagic destruction of mitochondria." (PMID 23533695, 2013). "Autosomal recessive forms of Parkinson’s disease are caused by mutations in three genes: Parkin, PINK1, and DJ-1." (PMID 23626584, 2013). "Mutations in PTEN inducible kinase-1 (PINK1) induce mitochondrial dysfunction in dopaminergic neurons resulting in an inherited form of Parkinson’s disease." (PMID 23638067, 2013). "In agreement with this PINK1 and Parkin mutations are generally associated with early onset, relatively symmetrical parkinsonism." (PMID 23935950, 2013). "Pink1 is a mitochondrial kinase involved in Parkinson's disease, and loss of Pink1 function affects mitochondrial morphology via a pathway involving Parkin and components of the mitochondrial remodeling machinery." (PMID 22242018, 2012). "Several hereditary forms of Parkinsonism are caused by mutations in genes related to mitochondria, such as PINK1 and PARK2." (PMID 23346074, 2012). "Recently, the Drosophila ortholog of mammalian PGAM5 (dPGAM5) has been shown to exacerbate mitochondrial degeneration and dopaminergic neuronal cell death in a model of Parkinson's disease induced by mutation of the Drosophila PINK1 gene." (PMID 22848813, 2012). "The Parkin-PINK1 system thus monitors damaged mitochondria, and dysfunction of this mechanism is a possible cause of inflammation or Parkinson's disease." (PMID 22536251, 2012). "Loss-of-function mutations in either Parkin or PINK1 can result in familial recessive forms of Parkinson's disease." (PMID 22737587, 2012).
Parkinson disease (continued). "Taking these factors into consideration, we feel that PINK1 inhibitors would be associated with a lower risk compared with disease-causing Parkinson's disease mutations that inactivate PINK1." (PMID 22645651, 2011). "Mutations in three genes, coding for parkin, DJ-1 and PINK1, are the cause of recessive forms of parkinsonism." (PMID 21244648, 2011). "It is thus likely that short periods of exposure to compounds that inhibit PINK1 for cancer treatments would carry a reduced risk of Parkinson's disease compared with chronic long-term treatment." (PMID 22645651, 2011). "This has enabled us for the first time to investigate the substrate specificity of PINK1 and demonstrate that most Parkinson's disease-associated missense mutations ablate or markedly inhibit PINK1 kinase activity." (PMID 22645651, 2011). "We have employed PINKtide to probe the effect that Parkinson's disease-associated mutations exert on PINK1 kinase activity." (PMID 22645651, 2011). "Our results suggest that missense PINK1 mutations situated within the kinase domain exert their Parkinson's disease-causing effects by markedly suppressing kinase activity." (PMID 22645651, 2011). "Patients harbouring PINK1 mutations typically present with early-onset Parkinson's disease, with a mean age of onset in their 30s." (PMID 22645651, 2011). "This emphasizes the importance of identifying the key physiological substrates of PINK1 in order to understand how the loss of kinase activity leads to neurodegeneration in Parkinson's disease." (PMID 22645651, 2011). "Mutations in PINK1 and Parkin genes have been associated with the latter forms of Parkinson's disease." (PMID 21151574, 2010). "The R275W polymorphism in Parkin and the G411S polymorphism in PINK1 have only been identified as heterozygous polymorphisms in cases of Parkinson disease." (PMID 20126261, 2010). "Loss-of-function mutations in PINK1 and Parkin cause parkinsonism in humans and mitochondrial dysfunction in model organisms." (PMID 20126261, 2010). "Loss-of-function mutations in the PINK1 or parkin genes result in recessive heritable forms of parkinsonism." (PMID 20383334, 2010). "A variety of mutations in the PINK1 and Parkin genes cause early-onset Parkinson's disease in humans." (PMID 20126262, 2010). "The PINK1 gene encodes a kinase protein that contains an N-terminal MLS and mutations in PINK1 are linked to a recessive form of Parkinson's disease." (PMID 21092208, 2010). "Parkin and PINK1 mutations in early-onset Parkinson's disease: comprehensive screening in publicly available cases and control." (PMID 21034472, 2010). "Disease-causing mutations in PINK1 and/or Parkin disrupt this pathway at distinct steps, consistent with the pathway's importance for preventing early-onset parkinsonism." (PMID 20126261, 2010). "Understanding PINK1 subcellular localization will give us insights into PINK1 functions and how mutations in PINK1 lead to Parkinson's disease." (PMID 21092208, 2010). "Mutations in Parkin and PINK1 are inherited primarily in a recessive manner, and loss of their function is thought to cause early-onset Parkinson disease." (PMID 20126261, 2010). "Taken together, these findings suggest that PARK6 parkinsonism results from a loss-of-function of the PINK1 protein." (PMID 18560593, 2008). "Our findings give new insights into the underlying dysfunction of human dopaminergic neurons in PINK1 parkinsonism and sporadic PD, by utilising a truly representative in vitro cellular model of the disease." (PMID 18560593, 2008). "In order to investigate the role of PINK1 in Parkinson's disease, we studied PINK1 loss of function in human and primary mouse neurons." (PMID 18560593, 2008). "We examined families from Jordan with a high incidence of consanguineous marriages, a recessive pattern of inheritance, and at least one patient with parkinsonism in each family to investigate the significance of parkin and PINK1 mutations in the region." (PMID 19087301, 2008).
Parkinson disease (continued). "Mutations in the PTEN induced putative kinase 1 (PINK1) are implicated in early-onset Parkinson's disease." (PMID 17362513, 2007). "Recently, mutations in the PINK1 (PARK6) gene were shown to cause autosomal recessively transmitted early-onset parkinsonism." (PMID 16354302, 2005). "In addition, the protein products of two genes linked to recessive Parkinson disease (PD), PINK1 (PTEN induced kinase 1) and PRKN (parkin RBR E3 ubiquitin protein ligase), mediate the ubiquitination of depolarized mitochondria for clearance." (PMID 41277110, 2026). "The parasite’s ability to impair mitochondrial quality control mechanisms, such as mitophagy, mirrors the mitochondrial defects observed in Parkinson’s disease, where mutations in genes like PINK1 and PRKN disrupt mitophagy and lead to the accumulation of damaged mitochondria." (PMID 40149586, 2025). "Here, using microscopy, kinetic analysis, and molecular dynamics simulations, we analyzed three Parkinson’s disease–associated TM mutations; PINK1-C92F, PINK1-R98W, and PINK1-I111S, and found that mitochondrial localization and cleavage by the PARL protease were not significantly impaired." (PMID 39909370, 2025). "Considering the multifactorial etiology of Parkinson disease, studies conducted with the population in the Southeast of the country showed that the combination of the PINK1 SNP IVS1-7 A→G polymorphism with exposure to pesticides reduces the age of onset of the disease." (PMID 40243837, 2025). "Loss-of-function mutations in the PINK1 kinase lead to early-onset Parkinson’s disease (PD)." (PMID 40344059, 2025). "We next investigated if any PINK1/Parkin‐mediated mitophagy defect at cellular level may be associated with the parkinsonism that we observed in our patients." (PMID 41053928, 2025). "Finally, we examined α‐synuclein overexpression, a specific biomarker for parkinsonism with PINK1 defects and leading to dopaminergic loss, by quantifying mRNA abundance for its gene SNCA, as documented in several previous studies." (PMID 41053928, 2025). "The PINK1–Parkin mitochondrial quality control pathway is one of the most extensively studied mitophagy responses, since loss of function mutations in these proteins have been linked to early-onset Parkinson’s disease." (PMID 40680837, 2025). "PINK1 (PARK6) also have mutations that can cause autosomal recessive form of Parkinsonism." (PMID 39276929, 2024). "The confirmed interaction between Miro GTPases and PINK1 thus paved the way for the concept that Miro GTPases could have an influence on the progression of Parkinson’s disease, at least in the familial variants of the disease." (PMID 38607086, 2024). "However, its role in inherited cases of Parkinson’s disease, particularly those related to mutations in PINK1 and Parkin, is poorly understood." (PMID 39159312, 2024). "Parkin and PINK1 are two genes implicated in early-stage Parkinson’s disease (PD)." (PMID 39770531, 2024). "Parkin and PINK1 mutations are the main causes of autosomal recessive inheritance and early-onset Parkinson’s disease, with frequent Parkin mutations accounting for 77% of juvenile Parkinson’s disease and 10–20% of Parkinson’s disease in young patients." (PMID 39564524, 2024). "One form of mitochondrial stress could be caused by mutations in Pink1 and Parkin, which underlie rare forms of early-onset Parkinson’s Disease." (PMID 38462161, 2024). "Mutations in PINK1 and Parkin cause early-onset Parkinson’s Disease (PD)." (PMID 38565869, 2024). "Complete loss of PINK1 or PRKN function unequivocally leads to early-onset Parkinson disease, but it is debated whether impairments in mitophagy contribute to disease later in life." (PMID 38041584, 2024). "Interestingly, Pink1, a mitochondrial kinase implicated in Parkinson’s disease, also phosphorylates Drp1 at the same residue." (PMID 38637532, 2024).